TLR4 (toll like receptor 4)
Diseases named in the same sentence as TLR4 in open-access papers (continued):
Sharing a sentence is not in itself a finding about the gene and the disease.
myocardial ischemia (continued). "In myocardial ischemia/reperfusion (I/R) injury, VSIG4 inhibits M1 macrophage polarization by blocking TLR4/NF-κB signaling, thus preventing cardiomyocyte apoptosis." (PMID 40630963, 2025). "Overexpressing FTO in osteoarthritis models improves cartilage integrity and diminishes inflammation by modulating TLR4/MyD88/NF-κB signaling and NLRP3 inflammasome activity, which are relevant in myocardial ischemia/reperfusion injury." (PMID 39980685, 2025). "When enclosed within exosomes formed from MSCs, miR-182 specifically targets TLR4, thereby inhibiting the TLR4/NF-κB pathway and activating the PI3K/AKT pathway in the context of cardiac ischemia/reperfusion (I/R) injury." (PMID 39866781, 2025). "Berberine upregulated miR-340-5p and suppressed inflammation in myocardial ischemia and inhibited HMGB1/TLR4/NF-κB signaling in cardiomyocyte apoptosis and cancer-related myocardial impairment." (PMID 40525842, 2025). "In conclusion, this study demonstrated that the TLR4/NF-κB/NLRP3 pathway is involved in the anti-inflammatory and anti-myocardial ischemia/reperfusion injury (MIRI) properties of tilianin." (PMID 39508038, 2024). "Other anti-inflammatory mechanisms of KOR agonists include the inhibition of the Toll-like receptor 4 (TLR4)/NFκB signaling pathway, which was extensively studied in myocardial ischemia and reperfusion models." (PMID 38203748, 2024). "It mediates Toll-like receptor 4 (TLR4)/NF-κB signaling to promote myocardial injury and protect against myocardial ischemia." (PMID 38560521, 2024). "Previous experimental studies reported that RHO has an anti-inflammatory impact on myocardial ischemia by inhibiting the PI3K/Akt/mTOR pathway in vivo and the TLR4/NF-κB signaling pathway." (PMID 37888707, 2023). "For instance, in myocardial ischemia/reperfusion injury, RP105 plays a cardioprotective role by modulating both TLR2/TLR4 signaling pathways." (PMID 36136452, 2022). "For example, TLR4, the members of the Toll-like receptors (TLR) family in the Toll-like receptor signaling pathway, have been found to play a detrimental role in myocardial ischemia/reperfusion (I/R) injury." (PMID 27634901, 2016). "It has been reported that hearts from TLR4-defctive mice and TLR4 knockout mice display attenuated NF-κB activation and reduced production of pro-inflammatory cytokine (TNF-α, IL-1β and IL-6) following myocardial ischemia with a short period of reperfusion." (PMID 25823011, 2015). "In a rat model of myocardial ischemia/reperfusion injury, it was found that exosomes derived from M2 macrophages deliver microRNA-148a and alleviate myocardial ischemia/reperfusion injury by inhibiting thioredoxin interacting protein (TXNIP) and the TLR4/NF-jB/NLRP3 inflammasome signalling pathway." (PMID 38622659, 2024). "Furthermore, several studies have also demonstrated upregulation of TLR4 and MD2 in cardiac hypertrophy mice subjected to pressure overload, with similar results also observed in myocardial ischemia/reperfusion injury." (PMID 33324685, 2020). "Unlike Pentraxin, TLR4 has been reported to serve a pro-inflammatory role in murine myocardial ischemia-reperfusion injury." (PMID 21048961, 2010). "This led us to the conclusion that the regulation of myocardial cytokines differs from the regulation of serum cytokines, and that at least TNF and IL-1β are not primarily regulated through TLR4 in myocardial ischemia/reperfusion." (PMID 17592640, 2007). "Exogenous H2S can alleviate cardiac injury during acute myocardial ischemia by reducing inflammatory reaction in heart tissues under oxidative stress and ameliorate LPS-induced diaphragm dysfunction in rats by reducing inflammation through ROS/MAPK and TLR4/NF-κB signaling pathways." (PMID 31315822, 2019). "TLR4 mediates through a phosphoinositide 3-kinase dependent pathway, not through p38 MAP kinase to protect against myocardial ischemia/reperfusion injury." (PMID 20202224, 2010).
Allergy (82 papers, 2007 to 2025). An allergy is an immune response or reaction to substances that are usually not harmful. "The association of TLR2 and TLR4 with allergies is in line with previous studies, so we cannot exclude such influences on the modulation of TLRs in ERM severity." (PMID 39062973, 2024). "The relation between allergic diseases and a polymorphism in TLR4 rs1927911 has recently been suggested in a pool of six birth cohorts including in total 15,299 children." (PMID 37426425, 2023). "One study has highlighted that upregulated TLR4 in allergy is associated with increased levels of Th2 and anti‐inflammatory cytokines." (PMID 33900054, 2021). "Genetic variation in TLR2 and TLR4 is a major determinant of susceptibility to asthma and allergy in rural children." (PMID 30140427, 2018). "These lipid A variants are the most studied ligands of MD-2/TLR4, which is considered a molecular target related to several inflammatory pathologies but also to “modern-day” diseases, including allergies, asthma, and autoimmune disorders." (PMID 30154796, 2018). "In line with this, it is postulated that during early life, TLR4 activation is reduced and the development of Th1 immunity is also reduced favoring the balance toward Th2 responses and susceptibility to develop allergic diseases." (PMID 29867994, 2018). "Many association studies have reported that TLR polymorphisms and in particular TLR4 predispose to allergic diseases." (PMID 29093714, 2017). "Although the cell type contributing to a TLR4-mediated allergic reaction was not identified, immune cells such as DCs, macrophages, and endothelial cells were associated with an allergic reaction to Ni via TLR4." (PMID 21544193, 2011). "These facts strengthen the evidence of interaction between inflammatory responses caused by infection or allergy through TLR4 and FcεR1 receptors." (PMID 20707930, 2010). "However, discrepancies regarding TLR4 genetic polymorphisms and their beneficial or detrimental role in allergies have been reported." (PMID 40900225, 2025). "Previous studies have shown that TLR4-deficient mice exhibit increased susceptibility to allergic reactions, reduced macrophage activity, impaired intestinal motility, and decreased neuronal survival, highlighting the role of LPS-TLR4 signaling in maintaining innate immune homeostasis." (PMID 40230835, 2025). "Among them, TLR-4 is a key receptor implicated in allergic diseases and autoimmune responses." (PMID 40490797, 2025). "In addition, the healthy mice showed oral tolerance to food antigens, while allergy reactions persisted in the TLR4-deficient mice, indicating that intestinal microbes play an important role in food tolerance through the TLR4 signaling pathway." (PMID 36238281, 2022). "Deficiency in TLR4 or neutralisation of this trio of cytokines inhibits allergy development." (PMID 30423826, 2018). "Indeed, TLR4 acts on both innate immune cells and the airway epithelia, which need to communicate each other to cause allergic disease." (PMID 29093714, 2017). "Varying the concentrations or treatment time course of TLR4 agonist could regulate TLR3-associated allergic inflammation for a new strategy to combat allergic diseases." (PMID 27826297, 2016). "Although polymorphisms in TLR2 and TLR4 have been associated with changes in TLR and, consequently, with allergy risk, a direct causal relationship between these genetic variants and FA has not yet been established, possibly due to small sample sizes." (PMID 40900225, 2025). "Specifically, TLR4 agonists have demonstrated pre-clinical and clinical precedent for use in the treatment of allergy and atopic diseases." (PMID 39108263, 2024). "In a study analyzing the effects of 2’-FL on β-lactoglobulin (β-LG) induced allergy, the study found that 2’-FL can directly inhibit the TLR4/NFκB pathway in a dose-dependent manner." (PMID 39877362, 2024).
Allergy (continued). "We have shown in our previous study that intranasally administered E. coli O83 reduced allergy in a TLR4-dependent manner, suggesting the role of LPS." (PMID 37864211, 2023). "As the role of LPS displayed on the surface of EcO83-OMVs in the prevention of allergy is tantalising, we are planning a follow-up study using TLR4-defficient mice in an in vivo model of allergic airway inflammation." (PMID 37864211, 2023). "We have previously shown that E. coli O83 prevents the development of allergies in mice and that this effect depends on its interaction with TLR4." (PMID 37864211, 2023). "TLR-4 signaling also has been suggested to participate in allergic diseases as well as autoimmune responses." (PMID 38045687, 2023). "In particular, TLR4 activation altered the Th1/Th2 balance, resulting in amplification of allergic diseases." (PMID 36840208, 2023). "For example, single nucleotide polymorphisms (SNPs) in CD14, TLR4, and TLR2 genes have been correlated with the development of allergy sensitization and symptoms of allergy in children." (PMID 36704753, 2022). "Coagulation factors participate in the airway allergic disease, and the FCPs cleaved by proteases would engage innate TLR4 to induce immune responses." (PMID 35409170, 2022). "The purpose of this study was to characterize a novel allergen, Der f 38 binding to TLR4, and unveil its role as an inducer of allergy." (PMID 34445142, 2021). "A high level of TLR-4 has been shown in human allergies, which leads to activation by several bacteria products and some endogenous ligands, including heat shock proteins expressed during arterial injury." (PMID 34621380, 2021). "Although TLR4 has shown an anti-allergic effect in a few papers, it is considered to be an orchestrating factor related to the onset and alleviation of allergy." (PMID 34445142, 2021). "On the other hand, Der p 2 shows remarkable skin inflammation in TLR4 knockout (KO) mice, indicating that TLR4 has different roles depending on individual allergic disease." (PMID 34445142, 2021). "The importance of TLR4 in HDM-mediated allergy was shown through epidemiological and mechanistic studies." (PMID 33424827, 2020). "More insight into the role of TLR4 in HDM-mediated allergy was obtained by showing that TLR4 activation by HDM mediates ROS production is Der p 1-dependent." (PMID 33424827, 2020). "This becomes even more appealing under another point of view focused on the growing body of information describing the involvement of LPS and TLR4 in development of strongly emerging pathologies such as allergies." (PMID 30154796, 2018). "Several studies demonstrated the relationship between TLR2 and TLR4 signaling and the induction of Th1 or suppression of Th2 responses in allergic diseases." (PMID 29467764, 2018). "TLR4 agonists such as MPL® (monophosphoryl lipid A) seem to work effectively as allergy vaccines due to overexpression of TLR4 in asthmatic patients." (PMID 27274620, 2016). "In conclusion, we have uncovered a novel mechanism by which pollen/TLR4 innate immunity signaling initiates IL-33/ST2 allergic pathway that triggers Th2-dominant inflammation in pollen induced allergic diseases." (PMID 27796360, 2016). "As well as being the primary signaling receptor for bacterial endotoxin or lipopolysaccharide Toll-like receptor-4 function is modulated by numerous factors not only in the context of microbial pathogenesis but also autoimmune and allergic diseases." (PMID 25339952, 2014). "NGF promotes the TLR4 signaling-induced maturation of DCs through inducible p75NTR, an important event in allergy initiation." (PMID 24223644, 2013). "The pre- and post-allergy oral administration of XQLT to mice reduced the expression of TLR4 in the Der p-stimulated lung." (PMID 24223644, 2013). "The rationale to use LpA-stimulation was to assess one “master stimulus” representing microbial exposure (TLR4-stimulation) as “protective stimulus” against allergy development." (PMID 20967272, 2010).
Allergy (continued). "The MYD88 and TLR-4 genes are pivotal in immune signal transduction and inflammatory responses, and their interaction may dictate the intensity and progression of allergic reactions." (PMID 40870825, 2025). "In the jejunum of mice experiencing allergic reactions, the TLR-4 gene may similarly be activated by allergens, interacting with MYD88 to initiate a cascade of immune and inflammatory responses, thereby influencing the physiological state of the jejunum." (PMID 40870825, 2025). "The involvement of the TLR4 pathway was different in the two phases of the allergic disease." (PMID 37426425, 2023). "Numerous studies indicate a role of the TLR4 in the pathogenesis of allergic diseases." (PMID 36873048, 2023). "This study provides a possibility that the improvement effect of SD treatment on allergies and inflammation in AR mice may be related to the TLR4/TRAF6/NF-κB and IL-6/ROR-γt/STAT3 pathways and intestinal microflora modulation." (PMID 36276863, 2022). "In particular, TLR4 is an essential receptor in HDM-mediated allergy." (PMID 34445142, 2021). "Indeed, SNPs in the TLR4 gene are a risk factor for asthma, indicating that genetic variations of TLR family genes are related to susceptibility to allergic diseases." (PMID 30891811, 2019). "As IL‐33 release is ROS‐regulated, in part, by NADPH oxidase dual oxidase 1 (DUOX1) whose activity is elevated in allergic disease 9, we were interested to explore the activation of TLR4 by signaling mechanisms operated by Der p 1 and ligation of viral RNA‐sensing TLRs." (PMID 29542272, 2018). "One member of the TLR family, TLR4, has attracted particular attention in the context of allergic disease, both through the “hygiene hypothesis” in epidemiology and from mechanistic studies of immunology." (PMID 30423826, 2018). "In summary, DP has anti-apoptotic effects on neutrophils of normal and AR subjects through the TLR4/PKCδ/ERK/NF-κB pathway, and this finding may contribute to solution of the pathogenic mechanism of allergic diseases triggered by DP." (PMID 25243400, 2014). "The inhibitory effects of XQLT on NGF, p75NTR and TSLP may be associated with the TLR4 pathway, thus providing pharmacological targets for investigations into how XQLT affects the early phase of allergic reactions." (PMID 24223644, 2013). "In conclusion, XQLT may regulate NGF, p75NTR and TSLP via the TLR4 pathway in the early phase of an allergic reaction." (PMID 24223644, 2013). "Second, in terms of the development of allergic disease, both TLR2 and TLR4 exhibit polymorphisms in their genes that may alter the protective effect of microbial exposure as proposed in the hygiene hypothesis." (PMID 19662206, 2007). "Our previous study indicated that calprotectin may activate DCs and related signal transduction through the action of TLR4 to promote the differentiation of initial CD4 + T cells into Th2-type cells and then cause allergy-related immune responses, leading to the occurrence of allergies." (PMID 34903286, 2021). "However, it should be noted that different allergens were employed in these studies suggesting that the nature of the allergens might determine whether induction of allergy is TLR4/MyD88-dependent or independent." (PMID 29867994, 2018). "Previous studies have revealed four genetic polymorphisms in human TLR2, TLR4, and CD14, such as TLR2 rs1898830, TLR2 rs4696480, TLR4 rs4986790 and CD14 rs2569190, which play a role in the pathogenic mechanism of allergic diseases and the protection mechanism of maternal exposure to farming." (PMID 30140427, 2018). "The contribution of TLRs in allergic diseases was initially described by the finding, that recombinant Der p 2, one of the major HDM allergens, can promote TLR4 signaling by functional mimicking MD-2." (PMID 37426425, 2023). "The results demonstrated that allergens can result in allergic diseases accompanied by alteration of PEBP1, HMGB1 and TLR4 levels via miR-205-5P." (PMID 35635016, 2022).
Allergy (continued). "The contribution of activation of innate immunity via TLR4 and TLR2 signaling by microbial compounds comprised in HDM, such as LPS and β-glucans, to initiate Th2 polarization and HDM allergy was clearly confirmed." (PMID 33803079, 2021). "In the allergy, the role of NKT cells is to maintain the Th1/Th2 balance by involving endo- and exogenous ligands for toll-like receptor 4 (TLR4) in iNKT cells." (PMID 33435598, 2021). "However, despite increases in TLR4 expression, it is a well‐established clinical observation that patients with AR are more prone to develop infections and have an increased need for antibiotics, validating the inability for SP to prime the immune response in allergy." (PMID 33900054, 2021). "Inhibition of miR‐138‐5p in hMSCs enhanced its effects in attenuating inflammatory responses and allergic reaction in the ARAS model, which is presumably regulated by SIRT1 and the HMGB1/TLR4 pathway." (PMID 33973707, 2021). "Toll-like receptor 4 (TLR4) is one member of the TLR family that is expressed on airway epithelial cells and has drawn attention in the context of allergy due to its ability to bind LPS." (PMID 33424827, 2020). "We initially determined the importance of TLR4 for expression of mouse allergic airway disease induced by the fungal proteinase PAO (proteinase of Aspergillus oryzae), but extended this work to allergic disease induced by ovalbumin and viable A. niger spores." (PMID 32485866, 2020). "This leads to the ligation of Toll-like receptor 4, which is an indispensable component in HDM allergy development, and reactive oxidant-regulated gene expression." (PMID 30423826, 2018). "This has been shown with the TLR4 agonist monophosyphoryl lipid (MPL®), which has strong immunogenic effects and potential as an adjuvant for allergy vaccines." (PMID 27309732, 2016). "The contribution of TLR4 to the DP-induced mechanism is essential in allergic diseases, and TLR2 is activated by DP in alveolar macrophages, which is independent or dependent on TLR4." (PMID 25243400, 2014). "Further studies are required to identify how XQLT acts to prevent allergic reactions and to investigate the effects of XQLT on TLR4." (PMID 24223644, 2013). "Bifidobacterium-derived ILA, which was higher in the non-AAM fecal water, has anti-inflammatory and allergy protective effects on the immature immune system through AhR and TLR-4." (PMID 40954473, 2025). "During allergy development, DCs can be activated by a variety of TLR receptors, such as TLR5, a receptor for flagellin (a bacterial protein shown to be present in house dust mite extracts), or TLR4, which can be activated by a variety of airborne allergens." (PMID 41299703, 2025). "As HDM and S. mansoni are both known to activate TLR4, the TLR4–IFN-I axis might be an important mechanism enhancing DC maturation and Th2 responses in various pathologies, from helminthiases to allergic diseases." (PMID 29201030, 2017). "It was shown that TLR4 or TLR9 stimulation combined with FcεRI activation by anti-IgE resulted in a synergistic increase of IL-4, CXCL8, IL-13 and RANTES/CCL5, all of which are thought to enhance IgE-mediated responses, such as allergy or parasitic infection." (PMID 26870962, 2016). "Another study demonstrated increased production of tumor necrosis factor-alpha and interleukin-1 in cord blood mononuclear cells upon TLR2, TLR4, and TLR5 activation in newborns who later develop allergic diseases, suggesting a link between heightened perinatal TLR response and allergy development." (PMID 21912563, 2012). "It has been previously shown that activation of MDSCs through either TLR9 or TLR4 can further differentiate MDSCs into a myeloid cell that no longer has tumor suppressor activity or Th2 allergy inducing polarization." (PMID 21966467, 2011).